SMARCB1 (SWI/SNF related BAF chromatin remodeling complex subunit B1)
Description:
Core component of the BAF (hSWI/SNF) complex. This ATP-dependent chromatin-remodeling complex plays important roles in cell proliferation and differentiation, in cellular antiviral activities and inhibition of tumor formation. The BAF complex is able to create a stable, altered form of chromatin that constrains fewer negative supercoils than normal. This change in supercoiling would be due to the conversion of up to one-half of the nucleosomes on polynucleosomal arrays into asymmetric structures, termed altosomes, each composed of 2 histones octamers. Stimulates in vitro the remodeling activity of SMARCA4/BRG1/BAF190A. Involved in activation of CSF1 promoter. Belongs to the neural progenitors-specific chromatin remodeling complex (npBAF complex) and the neuron-specific chromatin remodeling complex (nBAF complex). During neural development a switch from a stem/progenitor to a postmitotic chromatin remodeling mechanism occurs as neurons exit the cell cycle and become committed to their adult state. The transition from proliferating neural stem/progenitor cells to postmitotic neurons requires a switch in subunit composition of the npBAF and nBAF complexes. As neural progenitors exit mitosis and differentiate into neurons, npBAF complexes which contain ACTL6A/BAF53A and PHF10/BAF45A, are exchanged for homologous alternative ACTL6B/BAF53B and DPF1/BAF45B or DPF3/BAF45C subunits in neuron-specific complexes (nBAF). The npBAF complex is essential for the self-renewal/proliferative capacity of the multipotent neural stem cells. The nBAF complex along with CREST plays a role regulating the activity of genes essential for dendrite growth (By similarity). Plays a key role in cell-cycle control and causes cell cycle arrest in G0/G1.
Synonyms: BAF47; INI1; SNF5L1; INI-1; Snr1; hSNFS; Sfh1p; RDT; PPP1R144; SNF5; CSS3; MRD15; RTPS1; SWNTS1
Tractability: Small molecule: a structure with a bound ligand is known. PROTAC: UniProt records ubiquitination sites on it; ubiquitination databases record sites on it; its protein half-life has been measured.
Gene: Protein-coding gene on chromosome 22 (23,786,931 to 23,838,009, forward strand). Ensembl gene ENSG00000099956.
Subcellular location: Nucleus
Subcellular location (Human Protein Atlas): Nucleoplasm; Nucleoli fibrillar center
Pathways (Reactome):
Chromatin organization: Formation of neuronal progenitor and neuronal BAF (npBAF and nBAF); Formation of the canonical BAF (cBAF) complex; Formation of the embryonic stem cell BAF (esBAF) complex; Formation of the polybromo-BAF (pBAF) complex; RMTs methylate histone arginines
Gene expression (Transcription): RUNX1 interacts with co-factors whose precise effect on RUNX1 targets is not known; Regulation of endogenous retroelements by Piwi-interacting RNAs (piRNAs)
Developmental Biology: Regulation of MITF-M-dependent genes involved in pigmentation
Gene Ontology:
Molecular function: ATP-dependent chromatin remodeler activity; DNA binding; identical protein binding; nucleosomal DNA binding; protein binding; RNA polymerase I core promoter sequence-specific DNA binding; Tat protein binding; transcription coactivator activity
Biological process: chromatin remodeling; host-mediated activation of viral transcription; positive regulation of glucose mediated signaling pathway; positive regulation of transcription by RNA polymerase II; positive regulation of transcription of nucleolar large rRNA by RNA polymerase I; single stranded viral RNA replication via double stranded DNA intermediate; transcription initiation-coupled chromatin remodeling; DNA integration; positive regulation of cell differentiation; positive regulation of double-strand break repair; positive regulation of myoblast differentiation; positive regulation of stem cell population maintenance; positive regulation of T cell differentiation; regulation of G0 to G1 transition; regulation of G1/S transition of mitotic cell cycle; regulation of mitotic metaphase/anaphase transition; regulation of nucleotide-excision repair; regulation of transcription by RNA polymerase II; RNA polymerase I preinitiation complex assembly
Cellular component: chromatin; fibrillar center; nucleolus; nucleoplasm; nucleus; protein-containing complex; SWI/SNF complex; bBAF complex; brahma complex; kinetochore; nBAF complex; npBAF complex; nuclear matrix; RSC-type complex; nuclear chromosome; XY body
Genetic constraint (gnomAD): Loss-of-function variants: 5 observed, 47.48 expected, observed/expected ratio (o/e) 0.11, 90% interval 0.054 to 0.22. The upper end of that interval is the gene's LOEUF score, 0.22, which puts it in group 1 of 6, group 1 being the genes least tolerant of losing a copy. Missense variants: 197 observed, 492.47 expected, observed/expected ratio (o/e) 0.4, 90% interval 0.35 to 0.45. Synonymous variants: 187 observed, 196.82 expected, observed/expected ratio (o/e) 0.95, 90% interval 0.84 to 1.07.
Gene-disease validity (ClinGen):
ClinGen rates the evidence that SMARCB1 causes each of these diseases.
Coffin-Siris syndrome (autosomal dominant): Definitive. Coffin-Siris syndrome (CSS) is a rare congenital multi-systemic genetic disorder characterized by aplasia or hypoplasia of the distal phalanx or nail of the fifth digit, developmental delay, intellectual disability, coarse facial features, and other variable clinical manifestations.
rhabdoid tumor predisposition syndrome 1 (autosomal dominant): Definitive.
Cancer hallmarks: suppression of growth (promotes); escaping programmed cell death (promotes); genome instability and mutations (suppresses); escaping programmed cell death; invasion and metastasis (suppresses); genome instability and mutations; change of cellular energetics
Homologues: Orthologues: dog SMARCB1 (100% identical), macaque SMARCB1 (100% identical), mouse Smarcb1 (100% identical), pig SMARCB1 (100% identical), rat Smarcb1 (98% identical), guinea pig SMARCB1 (98% identical), chimpanzee SMARCB1 (97% identical), zebrafish smarcb1a (93% identical), tropical clawed frog smarcb1 (92% identical), zebrafish smarcb1b (91% identical), Drosophila melanogaster Snr1 (65% identical), rabbit SMARCB1 (57% identical), and 1 more.
Diseases named in the same sentence as SMARCB1 in open-access papers:
SMARCB1 is named in the same sentence as 343 diseases in open-access papers, as found by Europe PMC text mining. Sharing a sentence is not in itself a finding about the gene and the disease. The quoted sentences say what the papers report.
rhabdoid tumor (297 papers, 2006 to 2026). An aggressive malignant embryonal neoplasm usually occurring during childhood. "They demonstrated a uniform loss of SMARCB1 protein in malignant rhabdoid tumors (MRTs), characterized by the classic pattern of germline loss of one allele followed by the somatic loss of the second allele." (PMID 41514521, 2025). "Typically, rhabdoid tumors can be classified as SMARCB1 deficient by demonstrating loss of INI-1 or as SMARCA4 deficient by demonstrating loss of BRG-1." (PMID 40036664, 2025). "similarly looked at SWI/SNF complex occupancy at SEs versus other distal sites in SMARCB1-deficient rhabdoid tumors." (PMID 39906560, 2025). "Complete INI-1 (SMARCB1) loss has been implicated in both pediatric and adult mesenchymal tumors, with pediatric malignant rhabdoid tumors (MRTs) and epithelioid sarcomas serving as prototypical examples." (PMID 40291911, 2025). "Approximately 25–35% of patients with malignant rhabdoid tumours (MRTs) carry a germline SMARCB1 alteration, which defines the Rhabdoid Tumour Predisposition Syndrome type 1 (RTPS1)." (PMID 40794298, 2025). "In SMARCB1-deficient rhabdoid tumors, loss of SMARCB1 caused differential effects on residual SWI/SNF occupancy at distal enhancers vs. SEs." (PMID 39906560, 2025). "Germline SMARCB1 PVs are associated with RTPS1 and the development of malignant rhabdoid tumours, schwannomatosis or neurodevelopmental disorders such as CSS and ID-CPH." (PMID 40794298, 2025). "Immunohistochemical studies later demonstrated loss of INI1 (SMARCB1) expression, which has become a defining diagnostic hallmark of rhabdoid tumors." (PMID 41514521, 2025). "Small-molecule BRD9 inhibitors have been shown to reduce the proliferation of SMARCB1-deficient rhabdoid tumor cells in vitro and induce G1 cell cycle arrest." (PMID 40115023, 2025). "Organoid and mouse models have indicated a specific early developmental time frame (E6–10) during which SMARCB1 loss-of-function leads to the formation of malignant rhabdoid tumours (see Sect." (PMID 40794298, 2025). "Mutations in the SMARCB1 tumour suppressor gene led to the development of epithelioid and rhabdoid sarcomas, and loss of SMARCB1 upregulates the expression of EZH2." (PMID 40011240, 2025). "SMARCB1/INI1 gene loss was first detected in soft-tissue tumors, such as renal and extrarenal malignant rhabdoid tumors, and atypical teratoid/rhabdoid tumors." (PMID 40115023, 2025). "While Tazemetostat is currently approved for SMARCB1-deficient epithelioid sarcoma, its application in rhabdoid tumors is under investigation." (PMID 40225550, 2025). "Early clinical trials have shown that Tazemetostat is well-tolerated and exhibits anti-tumor activity in SMARCB1-deficient tumors, with preliminary results suggesting efficacy in treating rhabdoid tumors." (PMID 40225550, 2025). "They noted significant downregulation of genes involved in neural and neural crest development in rhabdoid tumor samples and concluded that early progenitor cells, during a critical developmental window, are particularly susceptible to SMARCB1 loss." (PMID 41514521, 2025). "On a brighter note, inhibition of the H3K36 demethylase KDM2A was recently demonstrated to rescue resistance to EZH2 inhibition conferred by loss of the H3K36 methyltransferase NSD1 in SMARCB1-deficient rhabdoid tumor cell lines." (PMID 39403928, 2024). "SMARCB1-deficient tumors were first identified in malignant rhabdoid tumors and soft tissue tumors with poor prognoses that occur primarily in children." (PMID 39398818, 2024). "In rhabdoid tumor cell lines, which harbor inactivating mutations in the SMARCB1 gene, the SWI/SNF subunit BRG1—a synthetic lethal target in these cells—retains functionality in chromatin remodeling and regulation of the rhabdoid genome." (PMID 38473277, 2024).
rhabdoid tumor (continued). "As genomic profiling did not provide conclusive evidence for biallelic mutation as common cause of SMARCB1 inactivation, which is typical for rhabdoid tumors, we next investigated DNA methylation as an alternative mechanism for gene silencing." (PMID 39362842, 2024). "High immune presence (>80th percentile in the cohort) was observed across a range of tumor types including tumors with SMARCB1/A4 loss (chordoma, rhabdoid tumors), neuroblastoma, rhabdomyosarcoma and osteosarcoma, and high grade CNS tumors." (PMID 38755180, 2024). "In conclusion, this study reveals that the loss of SMARCB1 in rhabdoid tumors has specific consequences on mRNAs translation with potential to unveil new dependencies and future therapeutic strategies." (PMID 39542244, 2024). "Mutation of the SMARCB1 gene can cause one of the most aggressive and lethal cancers of early childhood and infancy, malignant rhabdoid tumor (MRT)." (PMID 38893160, 2024). "Loss of SMARCB1 in rhabdoid tumors has been associated with deregulation of the cyclin D-CDK4/6-RB axis, and CDK4/6 inhibitors were among the inhibitors with the most promising activity profile in ATRT cells." (PMID 39617889, 2024). "SMARCB1-deficient neoplasms represent a family of rare tumors, including amongst others malignant rhabdoid tumors, atypical teratoid and rhabdoid tumors, and epithelioid sarcomas." (PMID 38879847, 2024). "Rhabdoid tumors are driven by biallelic SMARCB1 inactivation; this loss disrupts the SWI/SNF chromatin remodeling complex, a natural antagonist of PRC2, leading to aberrant PRC2 activation." (PMID 39766049, 2024). "In rhabdoid tumors defined by loss of the SWI/SNF subunit SMARCB1, dysregulation of enhancer-mediated gene expression is pivotal in driving oncogenesis." (PMID 38473277, 2024). "After developing normally for 8 years, at age 10, she developed a malignant rhabdoid tumor (MRT) of the soft tissues with biallelic loss of SMARCB1." (PMID 38501975, 2024). "It is known that SMARCB1 loss needs to happen during certain developmental stages for rhabdoid tumor development, whereas mainly lymphomas and benign tumors are formed at later phases." (PMID 38499326, 2024). "In 1990, a deficit in the long arm of chromosome 22 was reported in malignant rhabdoid tumors, and mutations in SMARCB1 were identified in 1998." (PMID 39398818, 2024). "Mutations in the SMARCB1 gene were first described in rhabdoid tumors in 1998, evidencing for the first time the link between the SWI/SNF complex and human cancer." (PMID 38085333, 2024). "Recent preclinical evidence also supports dual EZH1/2 inhibition over EZH2-selective inhibition for the treatment of malignant rhabdoid tumors with SMARCB1 loss." (PMID 39403928, 2024). "In conclusion, this study reveals that the loss of SMARCB1 in rhabdoid tumors has specific consequences on mRNAs translation with potential to unveil new dependencies." (PMID 39542244, 2024). "Rhabdoid tumor demonstrates a loss of expression of integrase interactor 1 (INI-1) in immunohistochemistry studies, leading to SMARCB1 inactivation." (PMID 38066766, 2023). "Histologically, it can be challenging to distinguish epithelioid sarcoma from malignant rhabdoid tumour and other SMARCB1‐deficient tumours, whereas methylation profiling shows that they represent distinct entities and facilitates their classification." (PMID 37316954, 2023). "The regulatory landscape of malignant rhabdoid tumor (MRT) due to SMARCB1 loss remains to be explored." (PMID 38040699, 2023). "Biallelic loss of SMARCB1 underlies the key genetic abnormality in atypical rhabdoid/teratoid tumour (AT/RT) and malignant rhabdoid tumour, both aggressive cancers of childhood, as well as epithelioid sarcoma." (PMID 38275587, 2023).
rhabdoid tumor (continued). "Rhabdoid tumors with specific SWI/SNFc subunit mutations (mostly SMARCB1 and SMARCA4) have been shown to be associated with immune infiltration in the tumor microenvironment, monocytes/macrophages and CD8+ T lymphocytes being the two most predominant subtypes." (PMID 37446319, 2023). "Another recent study described two siblings with atypical teratoid rhabdoid tumors as having a pathogenic SVA-transposon insertion in SMARCB1." (PMID 37578974, 2023). "Biallelic-inactivating mutations in SMARCB1 were characterized in 1998 in malignant rhabdoid tumors, an aggressive type of pediatric soft-tissue sarcoma." (PMID 37446319, 2023). "SMARCB1‐deficient tumours also include malignant rhabdoid tumour, atypical teratoid and rhabdoid tumour, epithelioid malignant peripheral nerve sheath tumour, and poorly differentiated chordoma." (PMID 37316954, 2023). "In summary, PAX8 inhibition-resistant ccRCC cells display a global reduction in the kidney-specific cis-regulatory and transcriptional programs in favor of a dedifferentiated state which shares molecular features of SMARCB1 loss in pediatric rhabdoid tumors." (PMID 37554444, 2023). "SMARCB1 is a tumour suppressor, and its mutations have been associated with malignant transformation in rhabdoid tumors." (PMID 36478132, 2023). "Patients with HB with SCU component or low AFP should be assessed for SMARCB1 mutations and, if confirmed, treated as rhabdoid tumors." (PMID 36672416, 2023). "Pediatric patients with liver tumors difficult to classify histologically, with small undifferentiated histology but showing loss of SMARCB1 expression, should be diagnosed as rhabdoid tumors." (PMID 36672416, 2023). "The development of rhabdoid tumors is associated with the inactivation of the SMARCB1 gene (also called INI1), which encodes a critical component of the SWI/SNF ATP-dependent chromatin remodeling complex." (PMID 38062114, 2023). "SMARCB1 mutations are already present in the germline in up to 30% of patients, who then suffer from a rhabdoid tumor predisposition syndrome 1 (RTPS1; OMIM #609322)." (PMID 37450044, 2023). "In patient 4, the only detected and driving alteration was a homozygous loss of SMARCB1 (INI1) what is reflected in the related methylation class of a malignant rhabdoid tumor." (PMID 35864317, 2022). "Complete loss of SMARCB1/INI1 has most commonly been described in the English scientific literature as malignant rhabdoid tumors of renal origin within pediatric populations and proximal epithelioid sarcomas in adult populations." (PMID 36262954, 2022). "Having a germline mutation in one allele of either SMARCB1 or SMARCA4 increases the risk of developing rhabdoid tumors in children and schwannomas in adults because only one functional copy is present in each cell." (PMID 35892904, 2022). "We analyzed the methylome of seven primary RMC and compared it to other SMARCB1 deficient entities such as rhabdoid tumors (RT) and epithelioid sarcomas using 850 K methylation arrays." (PMID 36291828, 2022). "For example, SMARCA4-deficient ovarian small-cell carcinomas and SMARCB1-deficient malignant rhabdoid tumors display sensitivity to EZH2 inhibitors." (PMID 36361605, 2022). "Other SMARCB1 deficient cancers include epithelioid sarcomas (ES) and malignant rhabdoid tumors (MRTs), called atypical teratoid rhabdoid tumors (ATRTs) when developing in the central nervous system (CNS)." (PMID 36291828, 2022). "A central component of this complex is encoded by the SMARCB1 gene, and studies on patients with rhabdoid tumors have proven that they have a causative role for the pathogenic variants in this gene." (PMID 36295546, 2022). "Loss of SMARCB1 has been implicated in the initiation of cancers such as malignant rhabdoid tumor (MRT), atypical teratoid rhabdoid tumor (ATRT), and, more recently, renal medullary carcinoma (RMC)." (PMID 35892904, 2022).